RNF44 (ring finger protein 44)
Synonyms: KIAA1100
Tractability: PROTAC: ubiquitination databases record sites on it.
Gene: Protein-coding gene on chromosome 5 (176,526,700 to 176,538,025, reverse strand). Ensembl gene ENSG00000146083.
Subcellular location (Human Protein Atlas): Nucleoplasm
Gene Ontology:
Molecular function: protein binding; ubiquitin protein ligase activity
Biological process: protein ubiquitination
Genetic constraint (gnomAD): Loss-of-function variants: 24 observed, 42.28 expected, observed/expected ratio (o/e) 0.57, 90% interval 0.41 to 0.8. The synonymous counts are far from expectation, so gnomAD's model fits this gene poorly and the ratio says little. Missense variants: 529 observed, 495.83 expected, observed/expected ratio (o/e) 1.07, 90% interval 0.99 to 1.15. Synonymous variants: 262 observed, 213.49 expected, observed/expected ratio (o/e) 1.23, 90% interval 1.11 to 1.36.
Homologues: Orthologues: chimpanzee RNF44 (99% identical), macaque RNF44 (99% identical), pig RNF44 (96% identical), dog RNF44 (92% identical), mouse Rnf44 (91% identical), guinea pig RNF44 (79% identical), rat Rnf44 (77% identical), tropical clawed frog rnf44 (71% identical), zebrafish si:ch211-59o9.10 (17% identical). Paralogues in human: RNF38 (61% identical), RNF6 (21% identical), RLIM (18% identical).
Diseases named in the same sentence as RNF44 in open-access papers:
RNF44 is named in the same sentence as 7 diseases in open-access papers, as found by Europe PMC text mining. Sharing a sentence is not in itself a finding about the gene and the disease. The quoted sentences say what the papers report.
melanoma (2 papers, 2017 to 2023). A malignant, usually aggressive tumor composed of atypical, neoplastic melanocytes. "It has been reported that RNF44 is upregulated in melanoma cells due to hyperactivation of the ERK/AKT pathway." (PMID 36650953, 2023). "Collectively, our data illustrated that RNF44 participates in AMPK‐α1 degradation in BR melanoma cells, resulting in downregulation of autophagy and glucose uptake but upregulation of CAT‐2." (PMID 29094484, 2017). "Attenuated AMPK‐α1 and increased RNF44 levels were also found in melanoma tumors from patients who failed BRAFi or BRAFi/MEKi treatment." (PMID 29094484, 2017). "High levels of RNF44 corresponding to low levels of AMPK‐α1 appeared in BR xenografts and melanoma tumor samples from BR and BRAFi/MEK inhibitor (MEKi)‐resistant (BMR) melanoma patients." (PMID 29094484, 2017). "Furthermore, expression of ASS1, AMPK‐α1, or RNF44 represented as H‐score confirmed that BR/BMR tumor samples had 2‐7‐fold lower ASS1 and AMPK‐α1 than the average levels but fivefold higher RNF44 compared to naïve melanoma samples." (PMID 29094484, 2017). "Notably, RNF44 can be detected in BR or BMR melanoma tissues rather than naive samples, and its expression also inversely correlates with AMPK‐α1 in tissue samples." (PMID 29094484, 2017).
glioma (1 paper, 2023). A benign or malignant brain and spinal cord tumor that arises from glial cells (astrocytes, oligodendrocytes, ependymal cells). "Therefore, we further performed a Co‐IP assay by cotransfecting a plasmid containing RNF44 with a Flag tag or HIC2 with an HA tag into glioma cells to evaluate the interaction between HIC2 and RNF44." (PMID 36650953, 2023). "Our findings suggest that HIC2 represents a tumor suppressor gene and prognostic biomarker for glioma progression and that overexpression of HIC2 inhibits the proliferation of glioma in vitro and in vivo by interacting with RNF44 and PTPRN2." (PMID 36650953, 2023).
liver cancer (1 paper, 2024). An epithelial or non-epithelial malignant neoplasm that arises from the liver. "RNF44 is a prognostic indicator of liver cancer, and its high expression is related to the poor prognosis of liver cancer." (PMID 38609663, 2024).
non-small cell lung carcinoma (1 paper, 2025). A group of at least three distinct histological types of lung cancer, including non-small cell squamous cell carcinoma, adenocarcinoma, and large cell carcinoma. "In this study, a novel circular RNA_515 (circ_515)/microRNA‐296‐5p (miR‐296‐5p)/RING finger protein 44 (RNF44) axis is identified to be closely linked to the pathogenesis of non‐small cell lung cancer (NSCLC)." (PMID 39995883, 2025).
oral squamous cell carcinoma (1 paper, 2024). "Down-regulation of MIR600HG increased the expression of miR-125a-5p and decreased the expression of RNF44 in oral squamous cell carcinoma (OSCC)." (PMID 38609663, 2024).
tumor (3 papers, 2017 to 2025). "The human genome contains two genes that are related to mura, RNF38 and RNF44, which have been associated with both pro- and anti-tumour cell activity and drug resistance." (PMID 40867527, 2025). "IHC showed an increased rate of Ki67‐positive cells in tumor tissues with sh‐circ_515 + miR‐296‐5p inhibitor, whereas the rate of Ki67 positivity decreased in the oe‐circ_515 + sh‐RNF44 group." (PMID 39995883, 2025). "Decreased miR‐296‐5p expression and increased RNF44 expression was observed in tumor tissues with sh‐circ_515 + miR‐296‐5p inhibitor." (PMID 39995883, 2025). "In vivo, the anti‐tumor effects of circ_515 knockdown were reversed by miR‐296‐5p, while the tumor‐promoting effects of circ_515 upregulation were abolished by RNF44 knockdown." (PMID 39995883, 2025). "The tumor growth was accelerated and tumor weight was increased following sh‐circ_515 + miR‐296‐5p inhibitor treatment, whereas tumor growth was inhibited and tumor weight was reduced in the oe‐circ_515 + sh‐RNF44 group compared to the oe‐circ_515 + sh‐NC group." (PMID 39995883, 2025).
cancer (1 paper, 2025). A tumor composed of atypical neoplastic, often pleomorphic cells that invade other tissues. "In conclusion, circ_515 may function as a prognostic marker for NSCLC whose upregulation enhanced the growth and invasiveness of cancer cells by interacting with miR‐296‐5p and activating RNF44." (PMID 39995883, 2025). "Circular RNA_515 may serve as a novel prognostic biomarker for NSCLC cells whose upregulation enhanced growth and invasiveness of cancer cells through sponging miR‐296‐5p and activating RNF44." (PMID 39995883, 2025).